TGFB2 (transforming growth factor beta 2)
Diseases named in the same sentence as TGFB2 in open-access papers (continued):
Sharing a sentence is not in itself a finding about the gene and the disease.
myocardial infarction (6 papers, 2014 to 2025). Gross necrosis of the myocardium, as a result of interruption of the blood supply to the area, as in coronary thrombosis. "For example, Tgfb1 and Tgfb2 mRNA abundances were decreased by sappanone A. The Tgfb family critically regulates the inflammatory response, angiogenesis, and fibrosis under myocardial infarcts." (PMID 32967328, 2020). "The mechanism of Tgfb2 action in myocardial infarction needs further experimental verification." (PMID 35811717, 2022). "Similarly, in a rat model of myocardial infarction, all three TGFβ isoforms increase in the left ventricle after infarct, however TGFB2 had the largest fold increase, suggesting that TGFβ2 plays an important role in myocardial remodeling." (PMID 26918958, 2016). "The role of Tgfb2 methylation in myocardial infarction has not been reported in the literature." (PMID 35811717, 2022).
osteoarthritis (6 papers, 2018 to 2025). A noninflammatory degenerative joint disease occurring chiefly in older persons, characterized by degeneration of the articular cartilage, hypertrophy of bone at the margins and changes in the synovial membrane. "The expression levels of circCREBBP, screened by circular RNA sequencing during chondrogenic differentiation in adipose tissue-derived stem cells, and TGFβ2 were significantly increased in the cartilage of patients with osteoarthritis and IL-1β-induced chondrocytes." (PMID 36224344, 2022). "However, our current study reveals an up-regulation of ACAT1 expression in the synovium of patients with osteoarthritis, and a negative correlation with the levels of TGFB2 and IL-3." (PMID 40164659, 2025).
preeclampsia (6 papers, 2016 to 2025). Preeclampsia is a hypertensive disorder of pregnancy that is characterized by new-onset hypertension with proteinuria presenting after 20 weeks of gestation, and depending on mild or severe forms may initially present with severe headache, visual disturbances, and hyperreflexia. "Some findings associated with preeclampsia in this study, such as MTHFR and RGS5 have been previously associated with preeclampsia, while maternal serum levels of TGFB2 and ABCA1 are altered in preeclampsia as well." (PMID 31557190, 2019). "Cardiac gene expression of Vcam, Edn1, Ccr2, Ctgf, Tgfb1, Tgfb2, Tgfb3, Bnp, Cybb, Mmp2, Mmp9, Timp1, Camk2a, Slc9a1, Nr3c2, and Nr3c1 was not different between mice who had a normal pregnancy and mice who had a preeclampsia-like pregnancy at 5 or 10 weeks postpartum (respectively)." (PMID 40425613, 2025). "In contrast, it is reported that high TGFβ3 levels, but not TGFβ1 or TGFβ2 levels, can suppress trophoblast outgrowth, leading to shallow placental invasion and an increased risk of preeclampsia." (PMID 39791746, 2025).
proliferative vitreoretinopathy (6 papers, 2016 to 2026). Vitreoretinal membrane shrinkage or contraction secondary to the proliferation of primarily retinal pigment epithelial cells and glial cells, particularly fibrous astrocytes, followed by membrane formation. "TGFB2 upregulation was reported in eyes with iERM, proliferative diabetic retinopathy (PDR), and proliferative vitreoretinopathy (PVR), and it is associated with intraocular fibrosis." (PMID 27736918, 2016).
triple-negative breast carcinoma (6 papers, 2017 to 2024). An invasive breast carcinoma which is negative for expression of estrogen receptor (ER), progesterone receptor (PR), and human epidermal growth factor receptor 2 (HER2). "The BCBM is promoted by the interaction of astrocytes in the brain and the invading triple-negative breast cancer cells via TGF-β2 (Transforming Growth Factor-beta-2) produced by astrocytes and is responsible for ANGPTL4 expression upregulation/angiopoietin-like 4 (ANGPTL4)." (PMID 34944840, 2021). "It is shown that SRGN, due to its interaction with CD44, creates a positive loop with TGFβ2, regulating cellular migration, invasion, EMT and metastasis of the triple-negative breast cancer cell line MDA-MB-231." (PMID 38672477, 2024).
autism (5 papers, 2012 to 2025). Persistent deficits in social interaction and communication and interaction as well as a markedly restricted repertoire of activity and interest as well as repetitive patterns of behavior. "Additionally, we found DNA hypomethylation of site A of the TGFB2 promoter region in the postmortem brains of patients with autism and astrocytes of patients with autism associated with its increased expression." (PMID 38994948, 2024). "Regarding 5-hmC, we found an increase in the 5-hmC level of TGFB2 at site B in the neurons of patients with autism (~50%)." (PMID 38994948, 2024). "DNA methylation analyses of TGFB2 revealed significant promoter DNA hypomethylation in the astrocytes of patients with autism at site A." (PMID 38994948, 2024). "A recent study indicated that induced pluripotent stem cells (iPSC)-derived astrocytes from patients with autism also exhibited overexpression of immune relevant genes, such as TGFB1, TGFB2, and IL6 that was associated with DNA hypomethylation of TGFB2, IL6, and TNFA gene promoter regions." (PMID 40643545, 2025). "In postmortem brain samples, we found DNA hypomethylation of TGFB2 and IFI16 promoter regions, but DNA hypermethylation of HAP1 and SLC1A2 promoters in autism." (PMID 38994948, 2024). "Moreover, the astrocytes of patients with autism exhibited higher expression of TGFB1 and TGFB2 but reduced expression of proliferator genes such as CXCR4 and NURR1 in addition to RELN, EN2, HAP1, SIRT1, and GPX1 vs. controls." (PMID 38994948, 2024). "Considering TGFB2, similar to iPSC-derived astrocytes, the target CpGs of site A exhibited DNA hypomethylation in the postmortem brain samples of patients with autism vs. controls (~50%, Mean ± SEM in controls and autism, 1.16 ± 0.27 and 0.4805 ± 0.1, respectively, p = 0.05)." (PMID 38994948, 2024).
breast tumor (5 papers, 2015 to 2022). "In contrast to the role of TGFβ2 in osteoblast-induced dormancy, activated TGFβ1 could induce a mesenchymal phenotype and reawaken dormant breast tumour cells to rapid growth in the bone marrow." (PMID 36307871, 2022). "In our previous work, we have observed that breast tumor cells secrete high-level of TGFβ2." (PMID 28487507, 2017). "In addition, JUNB protein levels correlated with cyclin E1 and TGFB2 protein levels, suggesting that high JUNB protein levels may also promote aggressiveness of breast tumors by positively controlling their expression with consequences on both cell proliferation and invasion." (PMID 36494864, 2022).
eczema (5 papers, 2017 to 2024). "Our findings suggest that higher concentrations of TGFβ2 in mature human milk are associated with significantly increased risk of eczema reported by the age of 12 months." (PMID 28538696, 2017). "Increased TGFβ2 levels in HM are associated with a higher incidence of reported eczema, with detectable IL13 in colostrum showing protective effects for food allergy and sensitization." (PMID 28538696, 2017). "Some studies support this observation, having found increased TGFβ1 and TGFβ2 in colostrum associated with the eczema onset in infants." (PMID 28538696, 2017). "Infants having breast milk with higher levels of TGFβ2 were at significantly higher risk OR 1.04 (95% CI 1.01–1.06) of eczema development." (PMID 28538696, 2017). "High concentrations of TGFβ2 may represent a biomarker that may predict risk of eczema in breastfed infants." (PMID 28538696, 2017). "This may be a mechanism behind an association between the levels of TGFβ2 in HM and eczema." (PMID 28538696, 2017).
Hyperglycemia (5 papers, 2020 to 2025). An increased concentration of glucose in the blood. "Our study revealed that TGFB2 potentially mediates the communication between cone and microglia under hyperglycemia." (PMID 34434927, 2021).
pancreatic ductal adenocarcinoma (5 papers, 2021 to 2025). An infiltrating adenocarcinoma that arises from the epithelial cells of the pancreas. "High TGFB2 methylation was notably associated with improved OS in pancreatic ductal adenocarcinoma (PDAC) patients, showing a hazard ratio (HR) of 0.53 (95% CI: 0.334–0.843; p = 0.007)." (PMID 40565031, 2025). "This study uniquely demonstrates that TGFB2 methylation and expression are prognostic factors in pancreatic ductal adenocarcinoma (PDAC) in an age-dependent manner and correlate with clinical responses to TGFB2-targeting antisense therapy." (PMID 40650134, 2025). "The findings indicate that an antisense oligodeoxynucleotide specifically aimed at TGFB2 notably enhanced overall survival in younger patients with pancreatic ductal adenocarcinoma when compared to older patients." (PMID 40650134, 2025). "Our analysis underscores the critical role of TGFB2 in pancreatic ductal adenocarcinoma (PDAC) progression and prognosis, revealing significant age-dependent associations." (PMID 40650134, 2025). "Our study highlights the isoform-specific and age-dependent prognostic significance of TGFB2 in pancreatic ductal adenocarcinoma (PDAC)." (PMID 40650134, 2025). "It has been demonstrated that only the TGFβ2 isoform was predictive of OS in pancreatic ductal adenocarcinoma (PDAC)." (PMID 40650134, 2025). "In summary, we first demonstrated that N6-methyladenosine-modified TGFB2 triggers lipid metabolism reprogramming to confer pancreatic ductal adenocarcinoma gemcitabine resistance." (PMID 38914663, 2024). "Previous literature revealed that the upregulation of TGFB2 expression can mediate epithelial-mesenchymal transition of pancreatic ductal adenocarcinoma, and MET, IRS1, and BCL2L1 are also demonstrated to be related to PAAD initiation, progression, and metastasis." (PMID 34777634, 2021).
squamous cell carcinoma (5 papers, 2005 to 2022). A carcinoma arising from squamous epithelial cells. "Similarly, proliferating squamous cell carcinoma cells entered dormancy and induced TGFβ2 in a p38‐dependent manner upon treatment with atRA." (PMID 32392629, 2020). "The findings suggest that downregulation of MCM7, MAPT, TGFB2, and THBS1 by MS13 may inhibit cell proliferation and growth as well as metastasis and invasion in squamous cell carcinoma and adenocarcinoma NSCLC cells." (PMID 34299042, 2021).
acne (4 papers, 2021 to 2026). An inflammatory process of the sebaceous glands which is characterized by comedones, nodules, papules and/or pustules on the skin. "This includes rs1256580 at the TGFB2 locus and rs260643 as a candidate causal variant in the novel acne susceptibility locus at 2q12.3." (PMID 35132056, 2022). "A decrease in OVOL1 and TGFB2 expression in inflammatory acne papules compared to healthy skin of the same patients was also confirmed." (PMID 41351204, 2026).
chondrosarcoma (4 papers, 2010 to 2019). A malignant cartilaginous matrix-producing mesenchymal neoplasm arising from the bone and soft tissue. "In an immunohistochemical study, a correlation of TGFβ1 and TGFβ2 to the grade of chondrosarcoma has been described." (PMID 23088614, 2012). "Most noteworthy, VEGF, TGFB2 and CTGF, all of which are expressed in human chondrosarcoma, were also found to be expressed in SRC tumors." (PMID 20809981, 2010).
emphysema (4 papers, 2019 to 2025). "Tamoxifen-induced mesenchymal Gαq/11 gene deletion in adult mice resulted in emphysema associated with reduced TGFβ2 and elastin deposition." (PMID 37102682, 2023). "Our findings demonstrate that the emphysema-associated variant rs1690789 is located in an active gene regulatory region in human lung fibroblasts that interacts with the promoter region of TGFB2 and regulates TGFB2 expression." (PMID 31343404, 2019). "As an example, if someone has genetic mutations that alter the activity of a gene called TGFB2, their risk of developing emphysema increases." (PMID 31343404, 2019). "One of the top GWAS-eQTL colocalization signals associated with the moderate centrilobular emphysema pattern spans a 200 kb region that includes the 3’ UTR of TGFB2 and extends 100 kb downstream." (PMID 31343404, 2019). "This revealed that certain mutations near the TGFB2 gene were more common in patients with emphysema." (PMID 31343404, 2019). "Conditional association analyses identified two independent associations with moderate centrilobular emphysema near TGFB2, and both associations are in linkage equilibrium (i.e. low linkage disequilibrium) with the lead variant identified in a previous GWAS of severe COPD." (PMID 31343404, 2019). "Emphysema, another pathological state of COPD that can arise from genetic perturbations, has been linked to TGFB2 gene using GWAS." (PMID 38617561, 2024). "Previous research has established a connection between TGFB2 and emphysema through its role in fibroblasts." (PMID 38617561, 2024). "Via CRISPR/Cas-9 targeted deletion, we then demonstrated that a ~ 100 bp segment containing rs1690789 increases TGFB2 expression in primary human lung fibroblasts, providing novel evidence that genetic variation affecting TGF-β signaling contributes to the genetic predisposition to emphysema." (PMID 31343404, 2019).
endometrial cancer (4 papers, 2009 to 2021). Primary or metastatic malignant neoplasm involving the endometrium (mucous membrane that lines the endometrial cavity). "Conversely, Hypo-O-GlcNAcylation impaired endometrial cancer cell proliferation and wound healing, and down-regulated expression of pro-EMT genes (AHNAK, CALD1, and TGFB2)." (PMID 31080560, 2019). "Further, BPA up-regulates the expression of other TGFβ isoforms, TGFβ2 and TGFβ3 transcripts but not TGFβ1, in neural tissue and endometrial cancer cells, respectively." (PMID 24586524, 2014).
esophageal cancer (4 papers, 2018 to 2024). A primary or metastatic malignant neoplasm involving the esophagus. "TGFβ2 expression was found to be positively associated with the pathological stages of esophageal cancer." (PMID 32832354, 2020). "In this study, the data from gain‐ and loss‐of‐function experiments showed that TGFβ2 positively regulates esophageal cancer invasion." (PMID 32832354, 2020). "Taken together, these data suggest that TGFβ2 may be potentially useful as a diagnostic and prognostic biomarker for esophageal cancer." (PMID 32832354, 2020). "It is reported that imperatorin was verified as a novel TGFB2 inhibitor that can inhibit TGFB2 expression to suppress esophageal cancer metastasis, which also inhibited TGFB2 expression in PDAC gemcitabine-resistant cells." (PMID 38914663, 2024). "These analyses of TCGA data suggest that TGFβ2 may play a crucial role in metastasis of esophagus cancer." (PMID 32832354, 2020). "This work suggests the clinical and functional role of TGFβ2 in esophageal cancer metastasis." (PMID 32832354, 2020). "The expression level and clinical relevance of TGFβ2 in esophageal cancer remain largely unknown." (PMID 32832354, 2020). "Imperatorin also directly targets CREB1 to inhibit TGFβ2-ERK signaling and inhibit esophageal cancer metastasis." (PMID 33921660, 2021).
fibrosarcoma (4 papers, 2013 to 2024). A malignant mesenchymal fibroblastic neoplasm affecting the soft tissue and bone. "Similarly, in fibrosarcoma cells, syndecan 2 regulates TGFβ2 transcriptional regulation via Smad signaling to facilitate fibrosarcoma cell adhesion." (PMID 39334952, 2024). "Growth factors, including PDGF-BB, TGFβ2, and FGF-2, enhanced hyaluronan deposition to ECM and modulated HA-receptor expression in fibrosarcoma cells." (PMID 24083250, 2013).
heart failure (4 papers, 2013 to 2025). Inability of the heart to pump blood at an adequate rate to meet tissue metabolic requirements. "In nNOS−/− mice, the expression levels of heart failure-associated genes Cdk8, TGFβ2, and NOX4 and hypertrophic cardiomyopathy-related gene Nppa were analogous to levels in WT mice." (PMID 38628440, 2024). "ΔEPORE mice showed increased expression of two-fold or more of heart failure-associated genes Cdk8, TGFb2, Nox4, S100A, and SERCA2a." (PMID 38628440, 2024). "Compared to the Control group, the expression of Tln1 and TGFβ2 was significantly increased in the human patient heart failure group (SFigure 1)." (PMID 40819162, 2025). "We also validated Tln1 and TGFβ2 using human patient heart failure datasets(GSE116250)." (PMID 40819162, 2025). "However, while EPO treatment increased expression of these heart failure-associated genes in WT mice, EPO treatment did not change expression of heart failure-associated genes Cdk8, TGFβ2, and NOX4 and hypertrophic cardiomyopathy-related genes Nppa in nNOS−/− mice." (PMID 38628440, 2024).
Loeys-Dietz syndrome 4 (4 papers, 2014 to 2022). Any Loeys-Dietz syndrome in which the cause of the disease is a mutation in the TGFB2 gene. "Interestingly, one proband (GSD2201) was initially diagnosed with Paget’s disease or progressive diaphyseal dysplasia; eventually, he was found to carry a heterozygous variant in TGFβ-2 gene (c.220A>C, p.T74P) that could lead to Loeys-Dietz syndrome 4 (LDS4)." (PMID 34557487, 2021). "Furthermore, TGFB2 haploinsufficiency pathologically activates the TGF-β signalling pathway, leading to Loeys-Dietz syndrome type 4, which is characterised by arterial vasculopathy (arterial aneurysms, dissection and tortuosity), and other widespread connective tissue pathology, including hernia." (PMID 36584111, 2022).
meningioma (4 papers, 2000 to 2022). A generally slow growing tumor attached to the dura mater. "TGFβ signaling pathway was also found activated in fibroblastic meningioma, since multiple key genes in the pathway were up-regulated in tumor tissues by qRT-PCR, including TGFB2 (4.95-fold), TGFBR1 (2.43-fold), SMAD2 (2.82-fold), and SMAD4 (3.24-fold)." (PMID 23285163, 2012). "We noticed that genes such as TGFBI, SNAI1, MMP2, TGFB1, TGFB2, IGFBP7, and LTBP2 were upregulated by the treatment of M2-MDEs in meningioma cells and may contribute to tumor invasion and proliferation behavior." (PMID 35637794, 2022).
metastatic melanoma (4 papers, 2018 to 2025). A melanoma that has spread from its primary site to another anatomic site. "mRNA profiling of TGFβ2 in 124 melanocytic lesions including nevi, MIS, primary and metastatic melanoma demonstrated a progressive decline in TGFβ2 expression from metastatic lesions, to deeper primary lesions, to superficial lesions to nevi." (PMID 39825956, 2025).
pancreatic adenocarcinoma (4 papers, 2004 to 2025). "TGFB2 is found to be over-expressed in pancreatic adenocarcinoma." (PMID 29596435, 2018). "A TGFβ2-dependent increase in MUC4 expression in pancreatic adenocarcinoma and elevated levels of TGFβ2 transcripts in MUC4-expressing OT tumours suggest the involvement of this cytokine in MUC4 regulation by autocrine and/or paracrine manner in CD18/HPAF tumours." (PMID 14760381, 2004).
Sepsis (4 papers, 2012 to 2022). Sepsis is defined as life-threatening organ dysfunction caused by a dysregulated host response to infection. "Knockdown of TGFBR2 promoted cell viability but reduced cell apoptosis and inflammation in LPS-treated BEAS-2B cells, indicating that TGFB2 might be associated with the sepsis-related lung injury." (PMID 34126975, 2021).
viral infection (4 papers, 2013 to 2023). "Although the TGFβ2 factor, recently recognized as a key factor in fibrosis induction, did not result upregulated by virus infection in HUVECs, other factors belonging to TGFβ superfamily were promoted in particular by HHV-6A, including GREM1 and INHBE, IL-4, IL-5, TNF, and MMP9." (PMID 31878218, 2019).
amoebiasis (3 papers, 2021 to 2025). "The pathways involved in amoebiasis, cytokine‒cytokine receptor interaction and dilated cardiomyopathy involve several genes, such as Tgfb2 and Il1b, which are related to TGFβ signaling and NFκB signaling." (PMID 40474744, 2025). "It should be noted that we observed two genes concurrently enriched in three critical pathways: TGFB2 was enriched in the cell cycle, FoxO signaling, and amoebiasis pathways, while GADD45B was enriched in the cell cycle, FoxO signaling, and NF-kappa B signaling pathways." (PMID 33718368, 2021).